IL6 (interleukin 6)
Diseases named in the same sentence as IL6 in open-access papers (continued):
Sharing a sentence is not in itself a finding about the gene and the disease.
cancer (continued). "Various inflammatory mediators such as tumor necrosis factor (TNF), which augments microvascular leakiness, along with interleukin-1 (IL-1) and interleukin-6 (IL-6), known to suppress albumin production, contribute to the observed decrease in serum albumin among cancer-afflicted individuals." (PMID 40034601, 2025). "HnRNPs participate in cancer-related pathways including DNA repair and IL6/JAK/STAT3 signaling." (PMID 39868801, 2025). "Interestingly, the degree of IL‐6 secretion varied among cancer cell lines, with HEY‐CM inducing the highest levels, followed by OV‐90‐CM and SKOV3‐CM." (PMID 40255916, 2025). "A small study in 1994 involving six cancer patients demonstrated that plasma ADH levels rose in all patients two hours after IL-6 injection, suggesting that this inflammatory cytokine may directly induce SIADH." (PMID 40282292, 2025). "Notably, the SW1116 cancer cell line showed the most pronounced response to 5-FU, with a continuous decline in IL-6 levels throughout the exposure period." (PMID 41256010, 2025). "The IL-6–JAK–STAT3 pathway promotes survival, stemness, epithelial-to-mesenchymal transition (EMT), metabolic reshaping, and immunosuppression via induction of PD-L1 and myeloid recruitment programs, placing IL-6 at the nexus of cancer cell fitness and microenvironmental control." (PMID 41440526, 2025). "Additionally, emerging investigations have shown that CRC-derived EVs carrying miR-181a-5p can trigger the activation of hepatic stellate cells (HSCs) into cancer-associated fibroblasts (CAFs) by targeting SOCS3 and stimulating the IL-6/STAT3 pathway." (PMID 40493409, 2025). "To assess whether the hepatic Pdk3 upregulation we observed in the CACS KL and LLC+IL-6 mice is a universal phenomenon or specific to only these models, we analysed liver Pdk3 expression in other mouse cancer models." (PMID 40275022, 2025). "Treatment with docetaxel has been shown to increase Ki-67 positivity in cancer cells in an IL-6–dependent manner, while neutralization of IL-6—particularly when combined with granulocyte colony-stimulating factor (G-CSF)—significantly reduces this proliferation-inducing effect." (PMID 40977686, 2025). "IL-6 positively correlates with MDSC levels in various cancers." (PMID 40109854, 2025). "ED can impair the functioning of the central nervous system, exacerbate dysregulation of the hypothalamic-pituitary-adrenal (HPA) axis, and elevate the production of pro-inflammatory cytokines(IL-6, IL-8), potentially contributing to both the progression and severity of cancer." (PMID 40786522, 2025). "This may be a protective effect since the activation of IL-6 can be useful to prevent cancer progression via senescence induction." (PMID 39940287, 2025). "SASP factors contribute to various aspects of cancer progression; IL-6 and IL-8 promote EMT." (PMID 41154660, 2025). "The spread of cancer cells may be prevented by vitamin K through the reduction in inflammation (for example, by decreasing IL-6 and TNF-α)." (PMID 41003423, 2025). "Besides IL-6, cancer cell–secreted Wnt5a induces IDO1 expression through β-catenin (CTNNB1) activation in DCs." (PMID 40789452, 2025). "In the context of cancer, many of the physiological signals sensed by hypothalamic neurons are frequently altered; these include inflammatory cytokines/chemokines, including interleukin (IL-6), glucose, and endocrine hormones, such as leptin and ghrelin." (PMID 40740866, 2025). "Cancer-related systemic inflammation activates pro-inflammatory cytokines, including interleukin (IL)-1, IL-6, and tumor necrosis factor alpha, which suppress appetite by acting on the hypothalamus and contribute to catabolic processes, including muscle degradation and lipolysis." (PMID 40627291, 2025). "Inhibition of local IL-6/TNF-α release from systemic tissues, including the bladder, through cholinergic anti-inflammatory pathways suppresses local inflammation in the bladder and reduces the risk of cancer." (PMID 40708946, 2025).
cancer (continued). "Moreover, vitamin D inhibits IL-6 production in cancer cells and in endothelial inflammation that sometimes accompanies cardiovascular events." (PMID 40218903, 2025). "Overall, pediatric evidence does not show a consistent association between UPF and IL-6; the only positive signal appears among childhood cancer survivors but requires confirmation." (PMID 41010537, 2025). "Additionally, to assess how FA affects inflammation in HepG2 cancer cells, we measured the increase in IL-6 levels in cells treated with LPS for 24 h." (PMID 40299525, 2025). "IL-6 plays a dual role in immune regulation and in cancer progression." (PMID 40650089, 2025). "IL-6 is upregulated and abundant in almost all types of tumors, which promotes tumorigenesis and facilitates the repair and induction of countersignaling pathways to protect cancer cells." (PMID 40075580, 2025). "Drugs targeting IL-6 exhibit limited activity in patients with cancer when used as monotherapy." (PMID 40165901, 2025). "A systematic review also implied that this cancer-enhancing crosstalk might be mediated by interleukin-6 (IL-6), tumor necrosis factor-alpha (TNF-alpha), vascular endothelial growth factor (VEGF), and other potential mechanisms waiting for exploration." (PMID 39875372, 2025). "IL-6 remains promising as a therapeutic agent in attenuating cachexia within several cancer subtypes, but a better understanding of its direct and indirect effects in cancer patients is mandatory." (PMID 41010454, 2025). "In cancer-induced bone pain, increased IL-6 in DRG neurons of female rats upregulated expression and activation of TRPV1 through triggering Janus kinase (JAK)/phosphatidylinositol 3-kinase (PI3K) signaling pathway, resulting in mechanical allodynia and thermal hyperalgesia." (PMID 40332543, 2025). "Third, whether IL-6 serves as a primary assessment tool for outcome measures in cancer patients undergoing MBI therapy remains unclear." (PMID 40281902, 2025). "IL-6 promotes cancer cell proliferation while G-CSF contributes to tumor immunosuppression." (PMID 39934876, 2025). "More importantly, EGR146–49, LCN250 and SOCS351 could be upregulated by IL-1α, IL-1β and IL-6 in immune or cancer cells by activating the NF-κB or STAT3 signaling pathway." (PMID 40523992, 2025). "IL‐6 is central to inflammation in both cancer and autoimmune diseases." (PMID 41208643, 2025). "IL-6, the main culprit of cytokine storm, is a pro-tumorigenic cytokine as it promotes cancer cell proliferation and migration, interrupts cancer cell dormancy, and worsens the prognosis of cancer patients through inhibition of autophagy." (PMID 41375068, 2025). "Interestingly, IL-6 is also involved in the pathogenesis of cancer through the promotion of the proliferation and survival of cancer cells as well as neoangiogenesis." (PMID 39858477, 2025). "CD4+ Th cells assist in activating CD8+ CTLs and also produce cytokines that indirectly contribute to the anti-cancer immune response, common pro-inflammatory cytokines include IL-1, IL-6, IL-8, and tumor necrosis factor-α (TNF-α), while common anti-inflammatory cytokines include IL-4 and IL-10." (PMID 40881864, 2025). "Moreover, by adjusting immunological trajectories to available CD8 + T cell and IL-6 data, our model predicted elevated pro-inflammatory compounds (such as GM-CSF) in both cancer and immunosuppressed patients." (PMID 40489562, 2025). "Furthermore, immunohistochemistry demonstrated a notable decrease in the expression of IL-6 and Ki67, underscoring the importance of targeting visfatin in developing effective cancer therapies." (PMID 40392374, 2025). "The CAFs promote L-OHP resistance in CRC through IL-6 secretion, enhancing cancer cell survival." (PMID 40718440, 2025). "Therefore, based on clinical and experimental evidence, drugs targeting IL-6 signaling are reasonable partners for cancer patients in combination therapy with immune checkpoint inhibitors." (PMID 40040705, 2025).
cancer (continued). "The PI3K/AKT/IL-6 pathway plays a pivotal role in cancer cell proliferation and survival." (PMID 39975921, 2025). "Fat cells secrete inflammatory mediators such as TNF-α and IL-6, which promote cancer induction." (PMID 40361337, 2025). "This approach allowed us to reveal the conserved pathogenic role of Upd3–JAK–STAT or IL-6–JAK–STAT signalling in cancer-associated metabolic disorder, highlighting a potential therapeutic strategy of targeting hepatic gluconeogenesis or PDK3 in IL-6-driven cancer cachexia." (PMID 40275022, 2025). "Additionally, interleukin-6 (IL-6) is a critical component of the cancer microenvironment, which can be secreted by cancer cells or their stromal counterparts, such as cancer-associated fibroblasts (CAFs)." (PMID 40624315, 2025). "Furthermore, CJME treatment decreased serum IL-6 levels in mice with the CT26-induced cancer cachexia model." (PMID 40469669, 2025). "Moreover, IFIT2 depletion in metastatic OSCC cells induced muscle atrophy and cancer cachexia in mouse xenograft models by promoting IL6 (interleukin 6) production." (PMID 40564154, 2025). "Our data strongly support the targeting of IL-6 signalling in cancer treatment." (PMID 39858048, 2025). "However, in the context of paraneoplastic syndromes, the deregulated IL-6 production by cancer cells yields increased blood concentrations and systemic symptoms of inflammation." (PMID 39754984, 2025). "The role of TGF‐β, TNF‐α, IL‐10, IL‐6, and chemokines is more complex, as they may promote or inhibit cancer in a context‐dependent manner." (PMID 40356340, 2025). "During acute inflammation, elevated levels of tumor necrosis factor-α, interleukin-1, and interleukin-6 may induce abnormal cell proliferation and malignant tumor progression." (PMID 40272695, 2025). "Among these, IL-6 emerged as the most consistently and markedly increased marker, suggesting it may be a central mediator of cancer-induced neuroinflammation, followed by IL-1β and TNF-α." (PMID 41155372, 2025). "Reducing IL-6 levels has beneficial effects in cancer therapy." (PMID 40733274, 2025). "The identification of shared DEGs such as CXCL10 and IL6 invites further investigation into their mechanistic roles, building on studies that have underscored the importance of chemokines in immune regulation and cancer progression." (PMID 40063597, 2025). "Significantly higher serum IL-6 levels were detected in patients with cancer inflammation." (PMID 41614883, 2025). "In contrast, pathological IL-6 elevations, such as in chronic inflammation, autoimmune disorders, atherosclerosis, and cancer, drive sustained fibrinogen upregulation, including an overrepresentation of the γ′ isoform, which is associated with a prothrombotic phenotype." (PMID 41157266, 2025). "Dietary vitamin K (phylloquinone) consumption has been documented to have an inhibitory effect on systemic inflammation by reducing the level of pro-inflammatory cytokines, particularly tumor necrosis factor-α and interleukin-6, a well-known factor for promoting the onset and development of cancer." (PMID 41003423, 2025). "IL-6 has been reported to promote cancer progression through multiple pathways." (PMID 40248695, 2025). "Interleukin-6 (IL-6) is a proliferation initiator for many types of cancer." (PMID 39822977, 2025). "Similarly, both cancer cell lines secrete IL-6 at baseline, with notably higher levels in the ACHN line (474 ± 7 pg/mL) than in the Caki-2 line (97 ± 3 pg/mL)." (PMID 41007670, 2025). "Thermogenic tissues are major sources of IL‐6; thus, we hypothesized that changes in housing temperature might affect the cancer‐induced IL‐6 production in such tissues." (PMID 40237521, 2025). "The potential therapeutic value of targeting IL-6 existsfor oral oncology since anti-IL-6 agents are already being tested for cancer patients in other treatment settings.Researchers face limitations when they use IL-6 marker despite its potential value for diagnostics." (PMID 40978585, 2025).
cancer (continued). "Silencing IL-6 led to reduction in migratory potential for cells under compressive stress, suggesting that solid stress-induced cancer cell migration in compressed MDA-MB-231 cells could be dependent on IL-6 levels." (PMID 40371393, 2025). "By its hand, exercise modulates IL-6 in a complex way, which may partially explain its benefits on cancer fatigue." (PMID 40824310, 2025). "Aberrant IL6 expression has been reported in several diseases, including cancer." (PMID 40143084, 2025). "With no binding to Fc receptors, cadonilimab shows minimal antibody-dependent cellular cytotoxicity, antibody-dependent cellular phagocytosis, and interleukin-6 (IL-6)/IL-8 release, all of which may increase its safety in the treatment of cancer." (PMID 41293180, 2025). "In summary, DTT water extract protects muscle cells under cancer conditions through direct and indirect mechanisms, with vitamin B1 being a key functional ingredient that reduces IL-6 generation and aids muscle cell fusion against IL-6 treatment." (PMID 41226740, 2025). "Furthermore, the restoration of the STAT3 pathway through the addition of exogenous IL-6 supports the notion that MCL exerts its anti-cancer effects by downregulating IL-6, thereby blocking STAT3 activation." (PMID 40051564, 2025). "Although IL-6 exerts pleiotropic effects on the immune system, it has emerged as a critical cytokine for the activation of immunosuppressive myeloid cells in cancer and may influence clinical responses to ICI57." (PMID 40161763, 2025). "Among them, IL-6 secreted by CAFs can reduce the response of cancer cells to chemotherapeutics, and stromal cell-derived factor-1 (SDF-1) secreted by CAFs can stimulate the malignant progression of pancreatic cancer and mediate the development of gemcitabine resistance." (PMID 40626005, 2025). "Based on this, we investigated whether cembranoid-mediated inhibition of IL-6 expression could suppress TGF-β-induced cancer cell invasion." (PMID 41373438, 2025). "The secretion of IL-6 was stimulated by inflammation or cancer processes." (PMID 40160826, 2025). "This may also reflect the impact of the intervention method on cytokine IL-6 in the cancer subgroup." (PMID 40281902, 2025). "These patterns also extended to IL-6 concentrations that similarly varied between VPCs: immunosuppressed patients had the highest maximal mean values of IL-6 of 60 pg/ml, followed by VPs in the cancer VPC, who were predicted to have an average peak value of 40 pg/ml." (PMID 40489562, 2025). "In addition to alterations in adiponectin and leptin levels, elevated levels of other adipokines, such as resistin, interleukin‐6 (IL‐6), and tumor necrosis factor‐alpha (TNF‐α), are associated with an increased risk of cancer." (PMID 40620232, 2025). "Recently, blockade of the IL-6 and IL-8 receptors (IL-6R and IL-8R) with a novel bispecific antibody significantly reduced metastatic burden in multiple preclinical mouse models of cancer." (PMID 41009413, 2025). "Given the known role of the IL-6/STAT3 pathway in enhancing cancer cell stemness, it was of interest to explore whether CD109-mediated IL6Rα/STAT3 pathway activation leads to increased stemness." (PMID 40317079, 2025). "These exosomes contain specific miRNAs, such as miR-20a-5p and miR-421, which promote IL-6 production and pancrea1ic cancer progression, respectively, by regulating the SIRT3/H3K9ac/HIF-1α axis.The cargo of CAF-derived exosomes is crucial for their effectiveness in cancer progression." (PMID 40038745, 2025). "The main finding of this study is that low, rather than high, post-ICI IL-6 levels are associated with a higher risk of developing irAEs in cancer patients treated with ICIs." (PMID 41019062, 2025). "The stimulation of the IL-6/STAT3 pathway is intricately linked to the processes of EMT and the manifestation of stem cell-like traits, which ultimately contribute to adverse outcomes in various individuals diagnosed with cancer." (PMID 40497987, 2025).
cancer (continued). "Additionally, IL-6 levels were increased in the cancer subgroup (SMD = 0.24; 95% CI, −0.29 to 0.76)." (PMID 40281902, 2025). "IL-6, markedly elevated in cancer patients and with levels correlating with disease stage and prognosis, exerts profound prothrombotic effects by inducing hepatic synthesis of fibrinogen and factor VIII, upregulating TF on monocytes, while suppressing anticoagulant protein S and antithrombin." (PMID 40725619, 2025). "Therefore, IL-6 can be considered a useful biomarker in different kinds of diseases, such as cardiovascular diseases, cancer, lung fibrosis, and chronic intestinal inflammation." (PMID 40422059, 2025). "The IL-6/JAK/STAT3 pathway is overactive in numerous cancer types." (PMID 40244228, 2025). "The excessive activation of JAK and its associated JAK/STAT signaling promotes cancer hallmarks such as proliferation, survival, and angiogenesis, in both the tumor and its surrounding environment, through the activation of STAT3, IL-6, IL-11, IL-22, IL-23, and interferon-γ (IFN-γ)." (PMID 40725854, 2025). "However, the overall impact of these cytokines on cancer is complex, given that some factors like IL-6 and TNF-α can have both pro-tumorigenic and anti-tumorigenic effects." (PMID 39427065, 2024). "Furthermore, comprehensive gene expression analysis in cancer sites revealed an upregulation of metabolism-related genes in the group with high serum IL-6 levels." (PMID 38510850, 2024). "Interestingly, this was associated with induced expression of the cytokine interleukin-6 (IL-6), which promotes cancer cell migration." (PMID 39439950, 2024). "Cytokines and mediators (such as IL-6 and IL-1 β) released by various cells in the microenvironment may lead to a vicious circle of osteolytic bone metastasis and expand cancer pain." (PMID 39679363, 2024). "So far, therapeutic agents against IL‐6, IL‐6 receptor (IL‐6R), IL-6-sIL-6R complex, or IL-6 downstream signal transducers have been developed, and determined to be effective in the intervention of inflammatory diseases and cancers." (PMID 38890694, 2024). "Our findings highlight that targeting the circNOX4/miR-329-5p/FAP/IL-6 axis might be a novel strategy for cancer therapy in NSCLC." (PMID 38459511, 2024). "Additionally, there appears to be a correlation between vitamin D and other inflammatory factors such as TNF-alpha, IL-1 beta, IL-6, IL-8, and IL-10, as well as its involvement in autoimmune diseases and cancers." (PMID 38337827, 2024). "Interleukin-6/STAT3 are key contributors to cancer growth and progression." (PMID 38519574, 2024). "Additionally, mesothelin induces the production of interleukin-6 (IL-6), B-cell lymphoma-extra large (Bcl-xL), and cyclin E, promoting cancer cell proliferation." (PMID 38396817, 2024). "Moreover, PN suppressed the IL-6-induced migration of cancer cells and specifically halted the development of tumors expressing a constitutively active STAT3." (PMID 38397437, 2024). "Interleukin-6 (IL-6) has also been identified as a potential factor that interacts with TNF-α or acts independently to induce systemic inflammation in the context of cancer cachexia." (PMID 38334644, 2024). "The GSVA revealed that the low-risk group exhibited enriched immune-related pathways (such as the IL6-JAK-STAT3 signaling and inflammatory response pathways), while the high-risk group exhibited enriched cancer-related pathways (such as PI3K-AKT-MTOR signaling and G2M checkpoint pathways)." (PMID 38442004, 2024). "Cytokines (such as PTHrP, interleukin (IL)-1, IL-6, and IL-8) derived from cancer cells could activate osteoclasts and subsequently activate the RANKL/RANK pathway which had been proven to be correlated with poor prognosis in cancer patients." (PMID 38698843, 2024).